PER1 (period circadian regulator 1)
Diseases named in the same sentence as PER1 in open-access papers (continued):
Sharing a sentence is not in itself a finding about the gene and the disease.
tumor (continued). "Our results show that Per2, but not Per1, plays an important role in the stromal regulation of tumor progression." (PMID 33123539, 2020). "Decreased expression of PER1 and PER3 in tumor tissue as such indicate poorer survival rate, decreased PER1 and high BMAL1 expression correlate with poorer outcome and liver metastasis, and high PER2 expression correlate with significantly better disease outcome." (PMID 31379749, 2019). "The result revealed a lower expression level of PER1 in tumor tissue compared to the non-tumor, adjacent tissue and the expression level decreased with the tumor progression." (PMID 31151182, 2019). "However, if there is decreased expression of both Per1 and Per2 in breast tumours the action of PER as a tumour suppressor becomes reduced." (PMID 27590298, 2016). "PER1, PER2 and PER3 were lower in the tumour when compared to neighbouring benign mucosa." (PMID 27465361, 2016). "PER1 and CRY1 were both up-regulated in neighbouring and tumour tissue compared to normal mucosa, while PER2 and PER3 were up-regulated in neighbouring mucosa and down-regulated in the tumour tissue." (PMID 27465361, 2016). "For example, the core clock genes PER1 and PER2 are known tumor suppressor genes, and their knockdown results in the doubling of tumor number and cancer growth; in contrast, overexpression of these genes decreases tumor number and cancer growth." (PMID 26253128, 2015). "Further analysis revealed that MMP-2 expression, MI, PI of tumor cells and tumor weight had negative correlation with PER1 expression." (PMID 23405233, 2013). "PER1 expression, MI, PI of BSCC cells and tumor weight confirmed to circadian rhythms." (PMID 23405233, 2013). "While the circadian genes PER1 and PER2 have been clearly shown to function as tumor suppressors in the mouse model, a recent study showed that epidermal deletion of BMAL1 in a transgenic mouse model which spontaneously develops squamous tumours leads to significantly fewer neoplastic lesions." (PMID 22470559, 2012). "Mice lacking Per1 and 2, Cry1 and 2, or one copy of Bmal1, all show increased spontaneous and radiation-induced tumor development." (PMID 20539819, 2010). "Circadian genes like PER1 and BMAL1, involved in DNA damage response, may exhibit altered expression in SCLC, potentially affecting the tumor’s response to therapeutic interventions such as radiation and chemotherapy, both of which interact with the circadian control of cell cycle and apoptosis." (PMID 39812541, 2025). "Moreover, IRE1α endoribonuclease is one of three main UPR signaling branches and decreases Per1 mRNA in tumor cells without affecting transcription." (PMID 36950678, 2023). "Indeed, CRY2, PER1, and RORA were downregulated, and TIMELESS was upregulated in tumor tissues, suggesting that TIMELESS may play a different role in HCC." (PMID 34745328, 2021). "To test whether both genes are also essential for the stromal regulation of tumor progression, we injected MC38 cancer cells to the portal vein of mice in which each of the Per genes (Per1, Per2) was knocked-out separately, and assessed metastatic colonization." (PMID 33123539, 2020). "Yet we find that T cell depletion does not compensate for the Per1–/–Per2–/–-driven inhibition of tumor growth, nor do we detect immune cell transcriptional signatures in early stages of metastases formation, suggesting that the adaptive immune microenvironment does not mediate this effect." (PMID 33123539, 2020). "Expression of the tumor-promoting inflammatory factor IL-6, immunosuppressive factor PD1, and PD-L1 increased, whereas expression of the immune factor TNF-α and body rhythm-related factors Per1 and Per2 decreased in the night-shift group, and the difference was statistically significant." (PMID 33083827, 2020). "In addition, clear differences in PER1 expression are evident in tumor tissues and noninvolved peripheral tissues." (PMID 31350984, 2019).
tumor (continued). "Moreover, it has been suggested that PER1 and PER2 function as tumor suppressors." (PMID 30518396, 2018). "This may suggest that tumor suppressing circadian genes (PER1,2,3, NPAS2) are particularly relevant for ER/PR negative tumorigenesis." (PMID 29958276, 2018). "MI, PI, MMP-2 mRNA and tumor weight had negative correlation with PER1 mRNA expression." (PMID 23405233, 2013). "PER1, PER2, PER3, CRY2 were found to be significantly down-expressed, while CLOCK, TIMELESS were over-expressed in the studied tumor samples compared to the non-tumor samples." (PMID 29958276, 2018). "Previous studies have identified PER1 and PER2, components of the negative arm of the molecular clock, as tumour suppressor genes." (PMID 30348208, 2018). "PER1 expression had negative correlation with MMP-2 expression, MI, PI of tumor cells and tumor weight." (PMID 23405233, 2013). "Additionally, for the genes PRKAB1, PRKAB2, PER1, PER2, and PER3, methylation was observed in all samples, regardless of the tumor grade." (PMID 39001398, 2024).
cancer (100 papers, 2010 to 2025). A tumor composed of atypical neoplastic, often pleomorphic cells that invade other tissues. "While circadian rhythms orchestrate various physiological processes, circadian genes such as Per1 and Per2 have been implicated in cell cycle regulation, DNA damage response, and apoptosis, which are critical in cancer development and progression." (PMID 39012661, 2024). "Recently, a colon cancer research indicated that the epigenetic regulator CBX4 was negatively associated with myeloid-derived suppressor cells and cancer-associated fibroblasts, and showed coordinated expression with PER1 and PER3 genes." (PMID 38813085, 2024). "Abnormality of the Per1 gene can lead to changes in the balance of apoptosis and proliferation and has the risk of causing cancer." (PMID 35723328, 2022). "In line with these roles in cell cycle progression and DNA damage response, the overexpression of PER1 has been shown to sensitize human cancer cells to ionizing radiation-induced apoptosis and cause significant growth reduction." (PMID 34221066, 2021). "CDKL2 is known to be involved in cell proliferation in human cancer cells, while PER1 gene of the circadian clock is known to regulate cell proliferation and apoptosis in association with human cancer cells." (PMID 34785720, 2021). "A total of 4 studies reported the association between the protein expression level of PER1 and cancer prognosis." (PMID 32849922, 2020). "Overexpression of PER1 made human cancer cells susceptible to DNA damage-induced apoptosis; conversely, inhibition of PER1 in the same cells decreased cell death." (PMID 33364523, 2020). "Abnormal expression of PER1 in mammals is not only associated with circadian rhythm disturbances, but is also closely correlated with carcinogenesis and the development of cancers." (PMID 26943040, 2016). "PER1 expression in OV was positively correlated with neutrophils, regulatory T cells (Tregs), M2 macrophages, cancer-associated fibroblasts, naïve B cells, activated dendritic cells, and resting CD4+ memory T cells, and negatively correlated with B cells and M1 macrophages." (PMID 34220965, 2021). "The E-box regulators BMAL1, CLOCK, CRY1, and PER1, as proteins, play a role in several cancers, and MB should be added to the list of those cancers." (PMID 40002179, 2025). "In recent years, the roles of PER1 in cancer, cardiovascular diseases, metabolic disorders, neurodegenerative diseases, and immune-related diseases have been gradually unveiled." (PMID 41451215, 2025). "Studies have shown that PER1 overexpression sensitizes human cancer cells to DNA damage-induced apoptosis, whereas PER1 inhibition attenuates apoptosis in similarly treated cells." (PMID 41451215, 2025). "In this study we show that LKB1 is a negative regulator of PER1 mRNA and PER1 protein expression, with increased PER1 mRNA and PER1 protein in immortalized LKB1-deficient lung epithelial cells, and in STK11mutant cancer cells and patient tumors." (PMID 40715535, 2025). "Alterations in the components of the circadian clock, including BMAL1, PER1/2, and CRY1/2, have been correlated with an increased risk of cancer development." (PMID 38469551, 2024). "While many cancer cell types continue to exhibit oscillations of the circadian clock, it was shown that deregulation of the key clock genes PER1, PER2, PER3, CRY1, CRY2, BMAL1, and CLOCK occurs in certain human malignancies." (PMID 38892035, 2024). "The repressive arms of the core circadian clock, including PER1 and PER2, are also implicated in cancer." (PMID 38469551, 2024). "By targeting PER1, the circadian oscillation of glycolysis is altered, potentially sensitizing the cancer cells to trastuzumab treatment and overcoming resistance." (PMID 39062777, 2024). "For instance, CLOCK was selectively expressed in ER+ cancer, whereas PER1 and TEF were highly expressed in both ER+ and HER+, and finally PER3 was expressed in HER2+ and TNBC." (PMID 39201344, 2024).
cancer (continued). "Our study found that the low expression of PER1 was significantly associated with high risk of recurrence in early-stage PTC, which was in good agreement with previous studies for other cancers." (PMID 38556856, 2024). "For example, it has been reported that PER1 enhances the sensitivity of cancer cells to ionizing radiation-induced apoptosis by inhibiting p21-mediated cell cycle arrest through induction of c-Myc." (PMID 38245510, 2024). "In contrast, KLF9 does not oscillate in entrained MDA-MB-231 cells and circadian expression of BMAL1 and PER1 was slightly irregular in the cancer cell line as well." (PMID 36823570, 2023). "The downregulation of PER1 increases the circadian amplitude of the daily peaks, which also increases cancer cell growth." (PMID 36731029, 2023). "In particular, the importance of PER1 has been highlighted by studies demonstrating that PER1 is downregulated in different types of human cancers and that its expression leads to growth suppression of human cancer cells." (PMID 33804124, 2021). "In line with previous findings showing that PER1 expression suppresses growth of human cancer cells, PER1-overexpressing tumors were smaller than controls, as indicated by tumors volume and weight and by gross histology." (PMID 33804124, 2021). "We found up-regulation of PER1 along with several deregulated circadian genes, enriching several important pathways and functions related to cancer onset and progression, such as epithelial-to-mesenchymal transition, cell cycle deregulation, and DNA damage." (PMID 34440260, 2021). "In contrast, suppression of PER1 expression by siRNA in IR-exposed cancer cell lines resulted in a reduction in the apoptotic rate." (PMID 34977153, 2021). "Recently, studies have shown that PER1 is silenced or inhibited in a variety of cancers, and that activation or upregulation of PER1 can effectively inhibit cancer cell growth and increase spontaneous cell death." (PMID 34220965, 2021). "Cancer cell lines exposed to ionizing radiation (IR) whilst overexpressing PER1 showed increased cell apoptotic sensitivity." (PMID 34977153, 2021). "For example, it has been reported that PER1 sensitizes cancer cells to apoptosis induced by ionizing radiation, by suppressing p21-mediated cell cycle arrest via c-Myc induction." (PMID 33804124, 2021). "This study not only confirmed the previous find that PER1 has an important suppressive effect on cancers but it was importantly found that PER1 regulates glycolysis and its regulatory mechanism in cancer cells for the first time." (PMID 33723221, 2021). "Our results showed that low Per1, Per2, Per3 and Npas2 expression played a distinct and crucial role in progression of cancers." (PMID 32437452, 2020). "Among them, there were 4 studies with a total of 476 cases that assessed PER1 protein expression in the prognosis of cancer." (PMID 32849922, 2020). "Our study suggested that low Per1, Per2 and Npas2 expression played a distinct and crucial role in progression of cancers." (PMID 32437452, 2020). "The research results demonstrated that the protein expression levels of PER1, PER2, and PER3 were significantly associated with the survival and prognosis of patients with cancer." (PMID 32849922, 2020).
cancer (continued). "Among these rhythm genes, PER1, PER2, PER3, and TIMELESS are the most frequently mutated genes in pan‐cancer." (PMID 31927791, 2020). "Per1, Per2 and Per3 were reported to play an important role in regulating cancer cell growth, proliferation and apoptosis." (PMID 32437452, 2020). "In conclusion, our meta-analysis provided evidence that low Per1, Per2and Npas2 expression played a distinct and crucial role in progression of cancers." (PMID 32437452, 2020). "Low expressions of Per1 and Per2 were related to poor OS in patients with cancers (Per1: HR=1.35, 95%CI: 1.06∼1.72, P=0.014 and Per2: HR =1.43, 95%CI: 1.10∼1.85, P=0.007), with high observed heterogeneity (Per1: Ι2=77.1%, P<0.001 and Per2: Ι2=63.1%, P=0.006)." (PMID 32437452, 2020). "Among them, there were 2 studies with a total of 89 cases that assessed PER1 mRNA expression in the prognosis of cancer." (PMID 32849922, 2020). "Evidence from initial research implicated PER1 as a regulator of the circadian clock; however, recent evidence has expanded the function of PER1 to include the promotion of apoptosis in cancer cells." (PMID 31350984, 2019). "For instance, PER1 was deleted in 16 cancers, while PER3 and CLOCK were lost in 15 and 12 cancers respectively." (PMID 31014368, 2019). "Decreased expression through hypermethylation of CpG islands or aberrant acetylation in the promoters of the core circadian genes Per1, Per2, and Per3 are reported in a spectrum of human cancers." (PMID 31409384, 2019). "The study suggests that down-regulated PER1 expression is correlated with more advanced cancer stages in patients with BSCC." (PMID 31151182, 2019). "Overexpressing and downregulating Per1 or Per2 inhibits and accelerates growth of cancer cells, respectively." (PMID 29607311, 2018). "Overexpression of Per1 and Per2 inhibits the growth of cancers cells and increases apoptosis in tumor cells." (PMID 28620312, 2017). "Numerous studies reported that individual molecular components of the circadian clock, such as BMAL1, PER2, or PER1 suppress proliferation or increase the sensitivity to anti-cancer drugs in different cancer cell lines." (PMID 28425940, 2017). "PER1 is highly correlated with the initiation and progression of cancer by regulating numerous downstream genes." (PMID 27602964, 2016). "We demonstrated that in vitro and in vivo cancer cells after PER1 knockdown, PER2, DEC1, DEC2, CRY1, CRY2 and NPAS2 were significantly down-regulated at the mRNA level, while PER3, TIM, RORα and REV-ERBα were significantly up-regulated." (PMID 27602964, 2016). "Previous studies have demonstrated that the expression of PER1 is decreased in many types of cancer." (PMID 27602964, 2016). "Abnormal expression of the clock gene PER1 is highly correlated with carcinogenesis and the development of malignant tumors." (PMID 26943040, 2016). "Future studies will likely clarify the specific signaling pathways affected by PER1 as well as the contribution made by aberrant PER1 expression to the development and progression of carcinomas." (PMID 26943040, 2016). "Up to now, there have been more studies focused on the molecular mechanisms by which PER1 regulates circadian rhythm than attempt to address the contribution of aberrant PER1 expression to the development and progression of carcinomas." (PMID 26943040, 2016). "Transfecting human cancer cell lines with Per1 and Per2 expression plasmids led to cessation of growth." (PMID 25760074, 2015). "Overexpression of Per1 and Per2 sensitized human cancer cells to DNA damage-induced apoptosis, while inhibiting expression of these genes in similarly treated cells reduced apoptosis." (PMID 25760074, 2015). "The PER1 and Timeless proteins interact with proteins involved in DNA damage response and Per1 overexpression suppresses growth of human cancer cell lines." (PMID 24875049, 2014).